FGFR1 (fibroblast growth factor receptor 1)
Diseases named in the same sentence as FGFR1 in open-access papers (continued):
Sharing a sentence is not in itself a finding about the gene and the disease.
schizophrenia (14 papers, 2011 to 2026). A major psychotic disorder characterized by abnormalities in the perception or expression of reality. "About half of them has been previously associated with schizophrenia in humans, such as Olig1, Fgfr1, Gpr17, Gna12, Abca2, Sox1, Dpm2, and, as a locus for de novo mutations, Rab2a." (PMID 39825014, 2025). "Brain organoids derived from schizophrenia iPSCs show reduced neuronal proliferation and development and decreased FGFR1 expression in cortical cells, conjugated with loss signaling of nFGFR." (PMID 36518994, 2022). "Neuron-committed cells from patients overexpressing FGFR1 reveal an association of nuclear FGFR1 with a large number of genes dysregulated in schizophrenia." (PMID 33860438, 2021). "Brain organoids derived from schizophrenia iPSCs show decreased proliferation and neuronal development and reduced expression of FGFR1 protein in cortical cells, accompanied by the loss of nFGFR1 signaling." (PMID 33195219, 2020). "Blocking and depleting FGFR1 with the antagonist PD173074 in the control organoids can cause cortical growth arrest similar to schizophrenia." (PMID 33195219, 2020). "The loss of nFGFR1 was limited to cortical cells, as FGFR1 remained highly expressed in the VZ and IZ of schizophrenia organoids throughout the 5 weeks of development." (PMID 30446636, 2017). "Supplementary Videos 2a and b further illustrate the expression of FGFR1 in subcortical cells and the loss of FGFR1 in cortical cells of schizophrenia organoids." (PMID 30446636, 2017). "Dysregulated FGFR1 signaling is implicated in cortical malformations and schizophrenia risk." (PMID 40806490, 2025). "The higher levels of miR-382 expression in schizophrenia patients might be associated with the lower levels of FGFR1 and SPRY4 expression." (PMID 34220567, 2021). "Interestingly, nuclear FGFR1 has been implicated in the disease pathogenesis of schizophrenia." (PMID 33860438, 2021). "An RNA sequencing analysis of the PFC suggested a dysregulation of numerous schizophrenia related genes including Olig1, Fgfr1, Gpr17, Gna12, Abca2, Sox1, Dpm2, and Rab2a in the rat model of psychosis." (PMID 39825014, 2025). "Cortical growth arrest similar to schizophrenia can be generated by antagonist PD173074 with FGFR1 knockdown in control organoids." (PMID 36518994, 2022). "In schizophrenia organoids, nuclear (n)FGFR1 was abundantly expressed by developing subcortical cells, but was depleted from the neuronal committed cells (NCCs) of the CZ." (PMID 30446636, 2017). "Both control and schizophrenia organoids displayed a less dense population of FGFR1 expressing cells in the IZ." (PMID 30446636, 2017). "In the present investigation, the cerebral organoid technology applied to control and schizophrenia iPSCs29,31,33 provided for the first time, an insight into the early stages of the telencephalic development and the role of FGFR1 in schizophrenia." (PMID 30446636, 2017). "At 2 weeks, strong FGFR1 expression and high density of FGFR1+ cells, were detected in the VZ of controls, as well as schizophrenia iPSC organoids (a4 and a5)." (PMID 30446636, 2017). "Elevated Fgfr1 expression in the prefrontal cortex co-occurs with schizophrenia (Volk, Edelson & Lewis, 2016)." (PMID 28674667, 2017). "We report for the first time, progression of the cortical malformation in schizophrenia and link it to altered FGFR1 signaling." (PMID 30446636, 2017). "Thus, the maldevelopment of the cortex in schizophrenia iPSC organoids was accompanied by a depletion of FGFR1 in the cortical cells." (PMID 30446636, 2017). "Notably, a transgenic mouse model of a related FGF gene, FGFR1, mimics physiological features of schizophrenia such as increased levels of dopamine and sensory impairment." (PMID 22016809, 2011).
schizophrenia (continued). "Literature-based analysis suggests that miR-9 exerts predominantly inhibitory effects on schizophrenia-related genes (e.g., IL1B, ABCB1, FGFR1) while promoting the expression of INS, indicating a potential protective role of miR-9 against schizophrenia." (PMID 40779062, 2026). "FGF signalling disturbances in mood disorders might be indirect, since the disruption of schizophrenia-associated proteins, such as the neuronal PAS domain protein 3 (NPAS3), correlates with a dramatic reduction in FGFR1 mRNA, and NPAS3 deficiency behaviourally resembles FGFR1 knock-out mice." (PMID 33860438, 2021). "This miRNA has been shown to target FGFR1 and SPRY4, two genes whose expressions were decreased in the olfactory cells obtained from patients with schizophrenia." (PMID 34220567, 2021). "Few or no FGFR1-expressing cells were detected in the cortex of the schizophrenia organoids in investigated iPSC lines." (PMID 30446636, 2017). "Indeed, the inhibition of FGFR1 signaling (the predominant FGFR expressed) with PD173074, depleted nFGFR1 in the CZ of control hESC organoids, and inhibited cortical development, similar to as observed in the schizophrenia organoids." (PMID 30446636, 2017).
triple-negative breast carcinoma (14 papers, 2012 to 2025). An invasive breast carcinoma which is negative for expression of estrogen receptor (ER), progesterone receptor (PR), and human epidermal growth factor receptor 2 (HER2). "Fibroblast growth factor receptor 1 (FGFR1) protein expression recently has been associated with poor prognosis of ER+/HER2-negative (HER2-) and triple-negative breast cancer." (PMID 28125801, 2017). "As an oncogene, FGFR1 deletion is less understood, while FGFR2 (10q26) missense mutation may be indicative of anti-FGFR2 inhibitor, as amplification or overexpression of FGFR2 was observed in 4% of triple negative breast cancers." (PMID 34203389, 2021). "Phosphoproteomic profiling across 18 triple-negative breast cancers (TNBC) and 1 luminal B PDX revealed considerable heterogeneity in kinase activation, but 1/3 of PDX exhibited enhanced phosphorylation of FGFR1, FGFR2 or FGFR4." (PMID 34344433, 2021). "A few reports showed that patients with FGFR1 overexpression in HR+/HER2- and triple-negative breast cancers had poor outcomes." (PMID 28125801, 2017). "Specifically, we illustrate that activation of both the inducible FGFR1 construct in mouse mammary epithelial cells and endogenous FGFR in the triple negative breast cancer cell line, HS578T, leads to expression of the chemokine CX3CL1." (PMID 23029290, 2012). "Identifying FGFR1 status could provide prognostic information and could help determine eligibility for targeted therapy, especially for patients with HR+/HER2- and triple-negative breast cancer." (PMID 28125801, 2017).
liver fibrosis (13 papers, 2013 to 2025). "NP603, which is an inhibitor of tyrosine kinase activity of FGFR1, inhibits the proliferation of myofibroblasts associated with liver fibrosis in rats." (PMID 23483937, 2013). "Autocrine FGF2 and the high expression of FGFR1 in HSCs and the activation of the FGF2/FGFR1 signaling pathway in HSCs have been demonstrated to play an important role in the regulation of liver fibrosis, cirrhosis, and tumor progression." (PMID 35951441, 2022). "For instance, FGF2 activates FGFR1 signaling in HSCs and upregulates the level of the CyGB gene to inhibit the transformation of HSCs into myofibroblasts and thereby alleviates liver fibrosis and cirrhosis." (PMID 35951441, 2022). "Depending on the LSEC response to liver injury, LSECs can promote liver regeneration by the CXCR7-ID1 pathway, or promote liver fibrosis via fibroblast growth factor receptor 1 (FGFR1)-CXCR4 pathway." (PMID 35087870, 2021). "While FGFR1 is a boon against liver steatosis, it acts as a bane in later stages of liver diseases, such as liver fibrosis." (PMID 34944593, 2021). "The link between FGFR1 angiogenesis and fibrosis is further buttressed by recent studies showing EC selective deletion of FGFR1 makes mice resistant to liver fibrosis." (PMID 24848261, 2014). "However, during chronic liver injury, LSECs switch to mediate hepatic fibrosis through FGFR1 signaling." (PMID 35618311, 2022). "Reciprocally, the physiological inhibition of FGFR1 was found to attenuate liver fibrosis." (PMID 34944593, 2021). "VEGF can interact with FGFR1 in the process of liver fibrosis." (PMID 33135394, 2020). "Furthermore, several lncRNAs target genes that have been reported to associated with HSC activated and liver fibrosis, such as CTGF, FGF2, FGFR1, IGFBP7 and NTN4." (PMID 29495545, 2018). "During chronic liver injury, LSECs persistently express fibroblast growth factor receptor 1 (FGFR1), supporting CXCR4-driven fibrotic angiocrine responses and promote liver fibrosis." (PMID 34064375, 2021). "In the canonical pathway for hepatic fibrosis/hepatic stellate cell activation, COL3A1, FGFR1, and IGFBP5 (P<0.01) were involved, which indicates similarity to the biological pathways already described in ULs." (PMID 23483937, 2013).
metastatic tumors (13 papers, 2014 to 2025). "Similar to OS, FGFR1 copy number gains are frequent in EWS, where patients with activating FGFR1 mutations present higher incidence of metastatic disease." (PMID 36839989, 2023). "Furthermore, FGFR1 amplification in ovarian serous carcinoma is associated with increased angiogenesis, metastatic disease, and overall poor survival." (PMID 24861215, 2014). "Compared with primary tumors, metastatic tumors more often displayed ZFHX4, FGFR1, MSI2, HIST1H1C, and TOP1 mutations, while MAPK7 mutations occurred only in primary tumors." (PMID 41301029, 2025). "Mutations in ZFHX4 (p = 0.0392), FGFR1 (p = 0.0436), MSI2 (p = 0.0437), HIST1H1C (p = 0.0467), and TOP1 (p = 0.0497) were significantly more common in metastatic tumors compared to primary tumors." (PMID 41301029, 2025). "In four of these 22 cases, samples from metastatic disease were available which also revealed FGFR1 amplification." (PMID 24861215, 2014). "Most recently, FGFR1 activation emerged as a crucial factor in regulating phenotypic plasticity during the transition from CRPC to neuroendocrine prostate cancer (NEPC), which is closely associated with metastatic disease." (PMID 38781024, 2024). "Therefore, the method has the potential to directly screen and detect FGFR1 amplification in a non-invasive and specific manner in plasma samples in patients with advanced metastatic disease, demonstrating significant tumor burden." (PMID 32517171, 2020). "Previous studies by our lab and others have demonstrated that expression of fibroblast growth factor receptor 1 (FGFR1) is dramatically increased during TGF-β-induced EMT and plays a critical role in metastatic tumor growth." (PMID 27825137, 2016). "In addition to suggesting the potential importance of FGFR1 and FAK1 inhibitors in metastatic disease, these agents may also warrant investigation as adjuvant therapy following surgical resection of localized high-risk disease to prevent metastasis." (PMID 28418903, 2017).
thyroid cancer (13 papers, 2014 to 2025). "We also show that lenvatinib directly inhibits the in vitro proliferation of thyroid cancer cell lines carrying mutations that activate RET or in which FGFR1 is overexpressed." (PMID 25295214, 2014). "Another study also identified the upregulation of FGFR1 expression in human thyroid cancer, compared to normal." (PMID 31408968, 2019). "Previous studies about the expression of FGFRs in thyroid cancer identified the upregulation of FGFR1 or FGFR4 in thyroid cancers, compared to normal tissues." (PMID 31408968, 2019). "Inhibition of FGFR1 in the thyroid cancer cell line FTC133 resulted in significantly decreased phosphorylation status of both investigated enzymes." (PMID 25880801, 2015). "With regard to thyroid tissue, the most studied receptor of this family, FGFR1, is overexpressed in differentiated thyroid cancer and in thyroid hyperplasia." (PMID 25880801, 2015). "Through the FGFR1 pathway, circRAPGEF5 modulates progression of thyroid cancer." (PMID 34153004, 2021). "Different from sorafenib, it was speculated that the effects of lenvatinib on thyroid cancer could be mediated by the inhibition of unique targets of lenvantinib, including FGFR1." (PMID 26062443, 2015). "Lenvatinib, a multitargeted kinase inhibitor of FGFR1–4, VEGFR1-3, KIT, RET, and PDGFR-β,4 has been proven effective for liver and thyroid cancers." (PMID 40747481, 2025). "In addition, the activity of lenvatinib through the inhibition of multiple RTKs may contribute to its antitumor activity against thyroid cancer cell lines with gene alterations (e.g., mutations or rearrangements) and overexpression of targeted RTKs, such as RET and FGFR1." (PMID 25295214, 2014). "FGFR1 and FGFR3 are expressed in well-differentiated thyroid cancers, and ATC cells overexpress FGFR4." (PMID 25295214, 2014). "Lenvatinib (E7080) is an oral multikinase inhibitor that targets VEGFR1‐3, FGFR1‐4, RET, c‐kit and PDGFRa, obtained considerable success in clinical trials of different cancer types, including NSCLC, thyroid cancer, gastric cancer, HCC, RCC and endometrial cancer." (PMID 33655556, 2021). "For example, in thyroid cancer, it activates TGF-β/Smad signaling pathway; in liver cancer, it serves as a competitive endogenous RNA (ceRNA) to promote tumorigenesis through regulation of FGFR1 expression by sponging miR-125a-3p." (PMID 32714094, 2020). "FGFR1 copy number increases were also not detected in PTC or other thyroid carcinomas." (PMID 37249797, 2023). "So far, FGFR1-mediated phosphorylation effects on LDHA and PKM2 have only been demonstrated in cell culture experiments without any relevance to human cancer tissue, especially thyroid carcinoma." (PMID 25880801, 2015).
rhabdomyosarcoma (12 papers, 2013 to 2025). A rare aggressive malignant mesenchymal neoplasm arising from skeletal muscle. "We had postulated in that study, that since MO3.13 oligodendrocyte cell line was created by fusion of oligodendrocytes with rhabdomyosarcoma cells, which overexpress FGFR1, it is likely that the results could be due to this fact." (PMID 36650549, 2023). "Among the rhabdomyosarcomas, alterations in FGFR1, KRAS, and MYC were detected." (PMID 37726478, 2023). "While it is possible that this is due to overexpression of FGFR1 in rhabdomyosarcoma cells, as documented in one study, nevertheless, it might reveal a novel role in B. burgdorferi-mediated pathogenic mechanisms." (PMID 28558791, 2017). "Although, we currently do not known whether AZA directly changed the DNA methylation status of the Fgf8 promoter, our results follow previous studies indicating that hypomethylation in primary rhabdomyosarcoma tumors was correlated with higher Fgfr1 mRNA expression levels in." (PMID 27200347, 2016). "Recently, FGFR::TACC fusions have been reported in a variety of non-epithelial cancers, including FGFR1::TACC1 fusions as a novel alternative genetic driver in rhabdomyosarcoma, and FGFR2::TACC2 fusions as a mechanism of multidrug resistance in TKI-treated gastrointestinal stromal tumors (GIST)." (PMID 39387893, 2025).
atherosclerosis (11 papers, 2013 to 2023). A disease characterized by the build-up of fatty material and calcium deposition in the arterial wall resulting in partial or complete occlusion of the arterial lumen. "Indeed, vascular inflammation is a hallmark of both transplant arteriopathy and atherosclerosis and in both settings there is a pronounced decrease in FGFR1 levels." (PMID 28181491, 2017). "It has been also documented that oscillatory shear stress limits fibroblast growth factor receptor 1 (FGFR1) expression in endothelium (protective signaling pathway preventing atherosclerosis) and stimulates transforming growth factor β (TGF-β) signaling." (PMID 35953533, 2022). "Previous studies indicated that EndMT is modulated by FGFR1 signaling, an important process during atherosclerosis." (PMID 34901211, 2021). "Atherosclerosis-prone areas of the arterial vasculature subjected to high shear stress demonstrate a reduction in FGFR1 expression and the appearance of low-level EndMT markers expression while atherosclerosis-resistant areas exhibit high FGFR1 expression." (PMID 28181491, 2017). "The link between FGFR1 expression and atherosclerosis was further demonstrated in ApoE null mice with endothelial-specific deletion of the FGF receptors signaling scaffold protein fibroblast growth factor receptor substrate 2α (FRS2α), which fully disrupts FGF signaling." (PMID 32478094, 2020). "As the role of FGF in atherosclerosis is much less documented than its role in restenosis, we checked the presence of FGF and its receptors in atherosclerotic lesions of apoE-deficient mice and found high expression of FGFR1 and the FGFR ligands FGF1 and FGF2." (PMID 24224032, 2013). "Interestingly, atherosclerosis-prone sites (areas of DSS) demonstrated lower level of FGFR1 staining compared to atherosclerosis-resistant regions of the arterial vasculature, suggesting that DSS downregulates FGFR1 expression." (PMID 32478094, 2020). "High expression of VEGF-A/VEGFR-2 and FGF-2/FGFR-1 but not of PDGF-BB/PDGFR-β may contribute to immature and inflammatory intraplaque angiogenesis and plaque instability in a rabbit model of atherosclerosis." (PMID 30125282, 2018).
esophageal squamous cell carcinoma (11 papers, 2015 to 2025). Esophageal squamous cell carcinoma (ESCC) is a type of esophageal carcinoma (EC) that can affect any part of the esophagus, but is usually located in the upper or middle third. "Further studies are warranted given that FGFR1 overexpression has been implicated in the poor prognosis of esophageal squamous cell carcinoma." (PMID 39138436, 2024). "FGFR1, a proven independent prognostic risk factor in patients with resected esophageal squamous cell carcinoma, was significantly differentially expressed in mutant ESCA samples (p-value = 7.56e-04), and high expression of FGFR1 was associated with poorer patient prognosis." (PMID 34079798, 2021). "A study of structural variations in esophageal squamous cell carcinoma (ESCC) found that chromothripsis leads to high-level amplification of FGFR1, LETM2 and NSD3 on chromosome 8." (PMID 38256018, 2024). "Additionally, PTK7 promotes proliferation, migration, and invasiveness of esophageal squamous cell carcinoma (ESCC) cells by activating fibroblast growth factor receptor 1 (FGFR1) and contributes to epidermal growth factor receptor (EGFR)/Akt signaling in TNBC cells." (PMID 39936972, 2025). "PTK7 is associated with proliferation, migration, and invasiveness, and activates FGFR1 independently of FGF in esophageal squamous cell carcinoma (ESCC) cells." (PMID 37569547, 2023). "The aim of this study was to investigate the frequency and the prognostic impact of FGFR1 amplification in patients with resected esophageal squamous cell carcinoma (ESCC) by using fluorescent in situ hybridization." (PMID 29088806, 2017).